CETP (cholesteryl ester transfer protein)
Diseases named in the same sentence as CETP in open-access papers (continued):
Sharing a sentence is not in itself a finding about the gene and the disease.
cardiovascular disease (97 papers, 2005 to 2026). "Cholesteryl ester transfer protein (CETP) inhibition has been associated with decreased risk of new-onset diabetes in past clinical trials exploring their efficacy in cardiovascular disease and can potentially be repurposed to treat metabolic disease." (PMID 37398493, 2023). "Previous association studies have indicated that CETP polymorphisms are associated with lower HDL-C concentrations in children with a family history of diseases of the cardiovascular system." (PMID 37833739, 2023). "Genetic variations in CETP have been studied, with the variations being associated with reduced CETP activities as well as reduced risks of cardiovascular diseases." (PMID 31597401, 2019). "Cholesterylester transfer protein (CETP) modulates the composition of various lipoproteins associated with cardiovascular disease." (PMID 30670016, 2019). "The genes ADIPOQ, ACE2, APOE and CETP are implicated in these processes and polymorphism in these genes have been reported responsible to cause cardiovascular diseases (CVD) in diabetic patients." (PMID 28761062, 2017). "The cholesteryl ester transfer protein (CETP) polymorphism I405V has been suggested to be involved in longevity and susceptibility to cardiovascular diseases." (PMID 27439317, 2016). "In order to analyze the association of the CETP rs5882 (I405V) SNP with the occurrence of cardiovascular diseases, we analyzed the 1517 PolSenior study participants, for whom detailed medical reports were available." (PMID 27439317, 2016). "Since it has been postulated that CETP rs5882 (I405V) genotypes influence HDL levels thereby potentially influencing the risk of cardiovascular diseases, we analyzed lipid levels according to CETP genotypes in the PolSenior group." (PMID 27439317, 2016). "The CETP locus is of considerable interest in light of controversies surrounding the relation of CETP genetic variation to risk of cardiovascular disease, and the failure of pharmacologic inhibitors of CETP to reduce this risk in recent clinical trials." (PMID 25898129, 2015). "For instance, CETP gene polymorphism can affect cardiovascular disease incidence, which could also affect MD outcomes." (PMID 39138561, 2024). "The study suggested that CETP polymorphism may be associated with a risk for cardiovascular disease in patients following an increased DII and DIL diet." (PMID 38474713, 2024). "Cholesteryl ester transfer protein (CETP) inhibitors are being developed for treatment of cardiovascular diseases, and vigilance for increased risk of AMD incidence or progression in treated patients may be appropriate." (PMID 36736292, 2023). "An abnormal lipid profile is considered a main risk factor for cardiovascular diseases and evidence suggests that single nucleotide polymorphisms (SNPs) in the cholesteryl ester transfer protein (CETP) gene contribute to variations in lipid levels in response to dietary intake." (PMID 35098451, 2022). "We here investigated the association of the CETP rs5882 (I405V) SNP with healthy aging and the susceptibility to cardiovascular disease in two study groups, the first group consisting of healthy blood donors from Lithuania and a second study group from Poland consisted of 1517 elderly subjects." (PMID 27439317, 2016). "Several studies have linked polymorphisms in the CETP gene to lipoprotein responses and risk for cardiovascular disease, and it has been hypothesized that these relations may be altered by weight loss." (PMID 16700901, 2006). "Therefore, low CETP activity is associated with high risks of cardiovascular disease." (PMID 38082436, 2023). "For example, high level of CETP was associated with a variety of cardiovascular diseases, and reducing the level of plasma CETP could increase the level of high-density lipoprotein cholesterol, so as to effectively reduce the risk of atherosclerotic cardiovascular diseases." (PMID 36192674, 2022).
cardiovascular disease (continued). "The interaction effect between the ADCY9 and CETP SNPs on both respiratory and cardiovascular phenotypes differs between the sexes, with effects on respiratory phenotypes limited to females and cardiovascular disease phenotype associations showing significant three-way sex-by-SNPs effects." (PMID 34609279, 2021). "Furthermore, analysis of cardiovascular outcomes in a Japanese cohort of 19,044 males and 29,487 females showed that subjects with both markedly elevated and mild-to-moderate HDL-C levels experienced fewer cardiovascular diseases independently of the status of the CETP gene mutation carrier." (PMID 34207236, 2021). "There is debate on whether CETP inhibition will reduce cardiovascular disease risk." (PMID 21609439, 2011). "Cholesteryl ester transfer protein (CETP), a key drug target in cardiovascular disease, primarily regulates plasma circulating levels of lipids (within high, low, and very-low-density lipoproteins)." (PMID 42231906, 2026). "In conclusion, on-target inhibition of CETP is anticipated to decrease cardiovascular disease in individuals of both European and East Asian ancestries." (PMID 38906890, 2024). "Cholesteryl ester transfer protein (CETP) is a promising therapeutic target for cardiovascular diseases." (PMID 38702788, 2024). "The involvement of CETP in both lipid transport and immune defense illuminates its multifaceted nature, although it also complicates the therapeutic targeting of CETP, especially in cardiovascular diseases." (PMID 39766344, 2024). "Given the robust LDL-C lowering effects of CETP-inhibition, research has understandably focussed on its potential implications for cardiovascular disease (CVD) prevention." (PMID 39415269, 2024). "We have also mentioned that it is possible to use inhibition of CETP in determining the potential of some natural compounds to be target drugs for use in the treatment of cardiovascular diseases." (PMID 39620013, 2024). "Plasma CETP levels are positively correlated with atherosclerotic cardiovascular disease (ASCVD) and increase the risk of other types of cardiovascular diseases (CVDs) and premature death." (PMID 39201274, 2024). "While CETP inhibition has been found to also significantly lower lipoprotein(a) levels, three large clinical trials investigating the use of CETP inhibitors in cardiovascular disease were terminated early due to toxicity or futility 83-89." (PMID 35836811, 2022). "Together with the early findings that humans with genetic deficiency of CETP had elevated levels of HDL and decreased levels of LDL, the development of CETP inhibitors as a potential treatment of cardiovascular disease has garnered great interest." (PMID 39872686, 2022). "Torcetrapib is the first CETP inhibitor developed to treat hypercholesterolemia and prevent cardiovascular disease." (PMID 36551995, 2022). "Low levels of CETP promotes HDL formation, thus, is associated with a lower risk of cardiovascular diseases." (PMID 36551995, 2022). "Cholesteryl ester transfer protein inhibitors (CETPis) have been studied primarily as a therapy to reduce cardiovascular disease, but have also been shown to reduce new-onset diabetes." (PMID 35441656, 2022). "HDL-cholesterol levels are inversely associated with the risk of cardiovascular disease (CVD) and epidemiological studies have shown that low blood CETP activity is associated with low CVD risk in certain populations." (PMID 35082691, 2021). "In humans, HALP due to CETP deficiency represents a unique setting in which the high HDL-C and cardiovascular disease relationship has been studied." (PMID 34207236, 2021). "CETP is well-known for its role in modifying lipid distribution between lipoproteins in circulation, which is correlated with the risks for cardiovascular disease." (PMID 35082691, 2021).
cardiovascular disease (continued). "In the Honolulu Heart Program, 3469 Japanese male subjects, carriers of two different CETP gene mutations, were evaluated for correlations between CETP deficiency, HDL-C levels and cardiovascular diseases." (PMID 34207236, 2021). "To date, the correlation between CETP and cardiovascular diseases is still controversial, as is its role on longer life expectancy." (PMID 34207236, 2021). "Polymorphisms in the CETP gene, which result in reduced CETP expression, are associated with high plasma HDL-C level and a low prevalence of cardiovascular disease." (PMID 31910446, 2020). "CETP inhibition has been a pharmaceutical approach to increase HDL cholesterol while decreasing LDL cholesterol and expecting a reduced risk of cardiovascular diseases." (PMID 30670016, 2019). "Inhibitors of CETP is under current investigation as potential drugs for reducing cardiovascular disease." (PMID 29973202, 2018). "As mentioned in the introduction, CETP has been considered as a potential target for elevating plasma HDL-C thereby treating cardiovascular disease." (PMID 28767652, 2017). "Cholesteryl ester transfer protein (CETP) has been identified as a potential target for cardiovascular disease (CVD) for its important role in the reverse cholesteryl transfer (RCT) process." (PMID 29112169, 2017). "As a result, CETP has become a promising drug target for the prevention and treatment of cardiovascular diseases." (PMID 27143480, 2016). "In the past decade, this property has driven the development of CETP inhibitors, which have been evaluated in large scale clinical trials for treating cardiovascular diseases." (PMID 27143480, 2016). "Inhibitors of proprotein convertase subtilisin/kexin 9 (PCSK9) and cholesteryl ester transfer protein (CETP) are both under current investigation as potential drugs for reducing cardiovascular disease." (PMID 27488210, 2016). "CETP inhibition has been regarded as a promising strategy for increasing HDL levels and subsequently reducing the risk of cardiovascular diseases (CVD)." (PMID 25737239, 2015). "High plasma levels of CETP are correlated with low HDL-C levels, and it has been implicated as a strong risk factor for cardiovascular disease, including MI." (PMID 24533069, 2014). "Due to their ability to promote positive effects across all of the lipoprotein classes, cholesteryl ester transfer protein (CETP) inhibitors are currently being developed as therapeutic agents for cardiovascular disease." (PMID 23801661, 2013). "Cholesteryl ester transfer protein (CETP) plays a major role in lipid metabolism, but studies on the association of CETP polymorphisms with risks of cardiovascular disease are inconsistent." (PMID 23039379, 2012). "Given the significant role of CETP in cardiovascular diseases, the broad interest of the topic is hoped to attract substantial interest to extend the present work." (PMID 22253581, 2012). "CETP inhibitors are a new class of preventive therapies for the treatment of cardiovascular disease." (PMID 19436720, 2009). "CETP inhibitors represent a new preventive therapy for cardiovascular disease through raising HDL cholesterol." (PMID 19436720, 2009). "Genetic variations in the cholesteryl ester transfer protein (CETP) gene are also interesting candidates to play an important role in cardiovascular disease." (PMID 16623947, 2006). "Therefore, sufficiently potent on-target inhibition of CETP is anticipated to prevent cardiovascular disease in both populations." (PMID 38906890, 2024). "It is also essential to highlight that the presence of the G allele in several populations has been associated with altered CETP protein activity, resulting in lower HDL-C levels, which may increase the risk of cardiovascular diseases." (PMID 39519516, 2024). "However, it should be noted that some studies have identified CETP agonists capable of improving cardiovascular disease." (PMID 37569628, 2023).
cardiovascular disease (continued). "This pejorative effect of CETP on plasma lipoprotein profile raised the hypothesis that CETP might represent a relevant target to prevent cardiovascular diseases." (PMID 36471375, 2022). "Analyses of the detailed interactions revealed several residues that might be critical for CETP function, which may provide important clues for the effective development of CETP inhibitors and treatment of cardiovascular diseases." (PMID 27143480, 2016). "Variation in CETP activity could influence HDL-C levels and thus contribute to increased susceptibility to cardiovascular disease such as MI." (PMID 24533069, 2014). "The Investigation of Lipid Level Management to Understand its Impact in Atherosclerotic Events (ILLUMINATE) trial exhibited an excess of deaths and cardiovascular disease in the group receiving the CETP inhibitor, torcetrapib and atorvastatin compared with atorvastatin alone." (PMID 25366166, 2014). "These preliminary findings suggest that CETP ASOs may represent an alternative means to inhibit that target and to support their continued development as a treatment for cardiovascular disease in man." (PMID 23801661, 2013). "Previously, the beneficial effect of an advantageous cholesteryl ester transfer protein (CETP-VV) genotype on lipoprotein particle size in association with decreased metabolic and cardiovascular diseases, as well as with better cognitive function, have been demonstrated." (PMID 17784782, 2007). "Variations in the CETP gene could be involved in the development of cardiovascular disease by increasing CETP activity and thereby reducing the cholesterol content of HDL relative to low density lipoprotein (LDL)." (PMID 16623947, 2006). "Therefore, CETP inhibitors may be promising for the prevention of cardiovascular disease, since they increase HDL and decrease LDL and ApoB." (PMID 36986146, 2023). "In particular, CETP enhances HDL remodeling from large (> 10 nm) to small (< 8 nm) HDL subclasses, and human CETP deficiency is associated with a predominance of large HDL particles displaying increased capacity to mediate cellular cholesterol efflux, a marker of cardiovascular disease risk." (PMID 34548543, 2021). "Because low levels of plasma CETP are associated with increased plasma HDL-cholesterol, therapeutic inhibition of CETP activity is considered an attractive strategy for elevating plasma HDL-cholesterol, thereby hoping to reduce the risk of cardiovascular disease." (PMID 28767652, 2017). "CETP: cholesteryl ester transfer protein; HDL-C: high-density lipoprotein-cholesterol; LDL-C: low-density lipoprotein-cholesterol; CVD: cardiovascular disease." (PMID 40264627, 2025). "Previous 2x2 factorial MR studies have identified combination therapies primarily within cardiovascular disease between PCSK9 and CETP inhibition, NPC1L1 and HMGCR inhibition, and IL-6 and PCSK9/CETP/NPC1L1 inhibition." (PMID 38962682, 2024). "Previous 2×2 factorial MR studies have identified combination therapies primarily within cardiovascular disease for PCSK9 and CETP inhibition, NPC1L1 and HMGCR inhibition, and IL-6 and PCSK9/CETP/NPC1L1 inhibition." (PMID 37398493, 2023). "Considering our previous research and interest in the relationship between lipids and cardiovascular diseases, we herein used ELISA to validate three differentially abundant proteins involved in cholesterol metabolism: fetuin-B, APOC3, and CETP." (PMID 35265678, 2022). "While all pharmacologic CETP inhibitors increase HDL-C, only those that decrease LDL-C also reduce cardiovascular disease risk." (PMID 36220816, 2022). "In this biobank study of 151 217 Chinese adults, CETP genevariants were associated with higher levels of high-density lipoprotein cholesterol butnot with lower levels of low-density lipoprotein cholesterol and were not associatedwith risk for cardiovascular disease." (PMID 29141072, 2018).
cardiovascular disease (continued). "Increasing levels of high-density lipoprotein (HDL) cholesterol through pharmacologicinhibition of cholesteryl ester transfer protein (CETP) is a potentially importantstrategy for prevention and treatment of cardiovascular disease (CVD)." (PMID 29141072, 2018). "In a recent trial, the CETP inhibitor torcetrapib, which raised HDL-C levels by approximately 70%, showed a paradoxical increase in cardiovascular disease outcomes." (PMID 21226953, 2011). "In recent years, antibodies have been raised against CETP as a therapy to lower plasma LDL-levels and to prevent cardiovascular disease." (PMID 15762995, 2005). "This suggests that low CETP activity is associated with poor cardiovascular disease (CVD) outcomes in males and that there are sex-dependent CETP splicing effects independent of HDL levels." (PMID 37974180, 2023). "Thus, inhibition of CETP is considered a promising therapeutic strategy to raise plasma HDL-C and prevent cardiovascular disease." (PMID 35265678, 2022). "Pharmacological interventions aimed at increasing HDL-C concentrations (fibrates, niacin, statins, inhibitors of the cholesteryl ester transfer protein –CETP–) have failed to reduce the incidence of cardiovascular disease (CVD)." (PMID 34945193, 2021). "Increased levels of CETP in women with Type two diabetes, but not in men, has been coupled to cardiovascular disease." (PMID 30958262, 2019). "Pharmacological CETP inhibition has therefore emerged as a prime target to modulate HDL levels, with an objective to become a potential treatment strategy for preventing various cardiovascular diseases." (PMID 25412509, 2014). "Inhibition of cholesteryl ester transfer protein (CETP) lowers plasma low-density lipoprotein cholesterol concentration and raises high-density lipoprotein (HDL) cholesterol, suggesting it might prevent cardiovascular disease (CVD)." (PMID 25187879, 2014). "In several clinical studies, it has not been proven that elevating HDL cholesterol (for instance, with niacin or CETP suppression) enhances CVD outcomes, and randomized Mendelian studies also show that levels of HDL-C are not prognostic for cardiovascular disease events." (PMID 35163256, 2022). "Nevertheless, HDL-raising therapies, such as cholesteryl ester transfer protein (CETP) inhibitors, failed to ameliorate cardiovascular outcomes in clinical trials, thereby casting doubt on the treatment of cardiovascular disease (CVD) by increasing HDL-C levels." (PMID 31979310, 2020).